AURKA (aurora kinase A)
Diseases named in the same sentence as AURKA in open-access papers (continued):
Sharing a sentence is not in itself a finding about the gene and the disease.
breast cancer (continued). "The first description of the AURKA 5’UTR-exons II and III sequences dates from 2000 and involved analysis of AURKA (STK-15) transcripts expressed in breast cancer cell lines." (PMID 40766465, 2025). "It has also been reported that overexpression of AURKA and CSTF1 are associated with detrimental prognosis of breast cancer patients." (PMID 40725120, 2025). "Studies have demonstrated that the expression of AURKA is upregulated in breast cancer, prostate cancer, ovarian cancer, pancreatic cancer, and other types of tumors." (PMID 38903715, 2024). "In this study, we aimed to characterize Aurora-A/AURKA in young breast cancer patients and evaluate its prognostic significance." (PMID 39198859, 2024). "For example, in breast cancer, the oncogene Aurora kinase A (AURKA) enhances IGF2BP2’s binding to m6A-modified transcripts without promoting its nuclear translocation." (PMID 39596216, 2024). "For example, research conducted in breast cancer shows that AURKA-mediated nuclear phosphorylation of YAP1 at this residue increases its stability and transcriptional activity." (PMID 38467828, 2024). "Our previous researches have demonstrated that elevated expression of AURKA in breast cancer promotes cell proliferation, invasion, stemness, and chemotherapy resistance." (PMID 38521813, 2024). "Activated MAPK signaling pathways induce AURKA accumulation in ERα+ breast cancer cells, leading to epithelial-to-mesenchymal transition (EMT)." (PMID 39334449, 2024). "Studies based on Aurora-A protein- and AURKA mRNA expression in breast cancer have implied that high Aurora kinase A expression is a strong and independent prognostic marker." (PMID 39198859, 2024). "Analysis of serum AURKA levels using ELISA kits in 119 women with breast cancer prior to neoadjuvant treatment demonstrated predictive value in the treatment response." (PMID 38590119, 2024). "Aurora kinase A immunohistochemical staining was performed on tissue microarrays of primary tumors from an in-house breast cancer cohort (n = 355) with information on clinico-pathologic data, molecular markers, and long and complete follow-up." (PMID 39198859, 2024). "Oncogenic AURKA influences breast cancer-related RNA splicing, interacting with YBX1 to promote GOLGA4 exon inclusion and with hnRNPK to induce RBM4 exon skipping." (PMID 38255791, 2024). "It suggests that breast cancer patients with high AURKA or CREBP1 performance should be more likely to receive hormonal therapy." (PMID 38612711, 2024). "Here, we investigate the expression of Aurora-A protein/AURKA mRNA expression in relation to clinico-pathologic information and outcome, evaluating the prognostic impact in young breast cancer patients, and the relation to biological processes." (PMID 39198859, 2024). "Aurora kinase A (Aurora-A) is considered as a key oncoprotein in breast cancer progression, where the overexpression has been associated with tumor growth, the basal-like phenotype, and poor prognosis." (PMID 39198859, 2024). "AURKA is aberrantly expressed in a wide range of human cancers, including breast cancer 12, ovarian cancer 13, cervical cancer 14, and hepatocellular carcinoma 15, and the aberrant expression of AURKA correlates with poor prognosis." (PMID 38994036, 2024). "As a result, AURKA is being actively pursued as a therapeutic target in breast cancer endocrine therapy." (PMID 39334449, 2024). "Prior research has indicated the possible effectiveness of combining the AURKA inhibitor Alisertib with immune checkpoint inhibitors in other tumor types, such as breast cancer." (PMID 38995006, 2024).
breast cancer (continued). "METABRIC cohorts < 50 years at breast cancer diagnosis (n = 368) were investigated for differentially expressed genes and enriched gene sets in AURKA mRNA high tumors stratified by age." (PMID 39198859, 2024). "To study the potential age-related differences of biological processes accompanying alterations in AURKA mRNA expression in breast cancer, we analyzed global gene expression data from primary tumors in breast cancer patients." (PMID 39198859, 2024). "It has also been shown that 62% of breast cancers overexpress AURKA, which is responsible for blocking the function of BRCA1 during G2, the phase of the cell cycle when its activity is crucial for regulating the centrosome." (PMID 38606093, 2024). "For example, in breast cancer cell lines, the inhibition of AURKA expression increases drug sensitivity to PI3K pathway inhibitors, which in turn induces apoptosis." (PMID 38673957, 2024). "Because AURKA drives centrosome amplification, aneuploidy, and chromosome instability, when AURKA is dysregulated, it can function as an oncoprotein in breast cancer progression." (PMID 38886738, 2024). "By multiple analytical approaches, our results provide evidence for increased tumor cell proliferation in breast cancer in AURKA-high tumors, in line with previous studies from our group and others." (PMID 39198859, 2024). "AURKA was originally named STK15/BTAK (Breast Tumor Amplified Kinase) due to amplification of chromosome 20q13 in breast cancer cell lines, the region where AURKA is located." (PMID 39198859, 2024). "The positive relationship between the apoptotic markers (cleaved caspase 3 and EGR1) and the efficacy of Taxol chemotherapy in breast cancer patients, highlights the role of Asp132-cleavage of AURKA." (PMID 38994036, 2024). "Previous studies have further suggested that high expression of AURKA (AURKAhigh) in breast cancer is a significant adverse prognostic factor for overall survival (OS)." (PMID 38903715, 2024). "Analysis of AURKA and hnRNPK protein expression levels in clinical breast cancer samples showed that hnRNPK expression was positively correlated with AURKA expression levels." (PMID 37415951, 2023). "Alisertib and barasertib have demonstrated promise as AURKA inhibitors in the treatment of breast cancer." (PMID 37711177, 2023). "The aberrant expression of AURKA, BUB1B, CCNA2, CCNB2, and PBK resulted in a poorer survival rate of breast cancer patients in the high-risk group having a survival rate of less than 2 years." (PMID 36980449, 2023). "The AURKA-splicing factor-aberrant splicing axis presented a relation to breast cancer with adverse outcomes." (PMID 37415951, 2023). "In the present study, we show that oncogenic AURKA promotes breast cancer-related RNA aberrant splicing in a context-dependent manner." (PMID 37415951, 2023). "Reciprocally, LIMK2 is required for AURKA-mediated cellular transformation in breast cancer, indicating that LIMK2 is a key oncogenic effector of AURKA in breast cancer malignancy." (PMID 36899941, 2023). "Our results add a critical piece to the puzzle of AURKA-related cancer pathogenesis by providing novel insights into breast cancer cell models of AURKA overexpression." (PMID 37386025, 2023). "Altogether, we provide evidence that AURKA and mitochondrial Complex V subunits cooperate to maintain cell metabolism in breast cancer cells." (PMID 37386025, 2023). "For instance, while AURKB was identified as one of the hub genes in Basal-like breast cancer, AURKA was recognized as a critical gene in HER2-enriched breast cancer." (PMID 37231064, 2023). "A differential level of mitochondrial AURKA was observed among various breast cancer cells used as models." (PMID 37386025, 2023). "It is well known that nuclear functions of AurkA correlate with an increase in transformed cells with breast cancer stem cell properties." (PMID 36797043, 2023).
breast cancer (continued). "This post-transcriptional modification affects many significant pathways in which the AURKA gene was enriched, such as the cell cycle, and played a key role in breast cancer growth and metastasis." (PMID 36980449, 2023). "GEPIA analysis disclosed that breast cancer patients have significantly higher expression of AURKA (4.0 vs. 1.5), AURKB (4 vs. 1), TTK (2.5 vs. 0.5), MELK (3.0 vs. 0.5), KIF20A (3.5 vs. 0.5) genes compared to healthy people." (PMID 37231064, 2023). "In summary, oncogenic AURKA executes its function on modulating breast cancer-related RNA splicing, and nuclear AURKA is distinguished as a hopeful target in the case of treating breast cancer." (PMID 37415951, 2023). "Taken together, our data show for the first time that Complex V inhibition in breast cancer cells induces a cell cycle arrest in G0/G1 involving the cell cycle-related kinase AURKA." (PMID 37386025, 2023). "Aurora kinase A (AURKA) is overexpressed in several types of cancer, including breast cancers, where it plays a role by aberrantly phosphorylating the proteins implicated in the cell cycle, ultimately leading to cell malignant transformation." (PMID 36899941, 2023). "Previous studies demonstrate that there is an abnormal high expression and activation of AURKA in breast cancer." (PMID 37781397, 2023). "Here, we show that oncogenic Aurora kinase A (AURKA) promotes breast cancer-related RNA aberrant splicing in a context-dependent manner." (PMID 37415951, 2023). "In breast cancer, AURKA is crucial to stem-cell renewal, and elevated expression is a survival predictor in ER-alfa positive tumors." (PMID 36752780, 2023). "To establish a putative link between G0/G1 arrest, loss in ATP levels and the abundance of AURKA, we asked whether cell cycle progression and ATP levels are enhanced in breast cancer cells with high levels of AURKA, and whether they are reduced in breast cancer cells with low levels of the kinase." (PMID 37386025, 2023). "In this study, we revealed that AURKA inhibitor MLN8237 upregulated the expression of PD-L1 in breast cancer by increasing the level of p-STAT3 and impeding the infiltration of CD3+ T and CD8+ T cells in tumor tissues, thus impaired antitumor immune response." (PMID 37781397, 2023). "RT-PCR was conducted to examine YBX1 and hnRNPK implicated in RNA splicing regulation by virtue of AURKA mediation, which showed that YBX1 knockdown promoted GOLGA4 exon skipping, whereas hnRNPK knockdown promoted RBM4 exon inclusion in breast cancer cells." (PMID 37415951, 2023). "An increased AurkA nuclear localization is reported in the literature as a prognostic marker for poor survival, particularly in breast cancer." (PMID 36797043, 2023). "In particular, in breast cancer AurkA nuclear localization has been proposed as a prognostic marker for poor survival and has been shown to associate with transcriptional up-regulation and stabilization of known oncogenes, such as FOXM1 and myc family members." (PMID 36797043, 2023). "Overall, we propose that targeting the AURKA/ATP5F1A/ATP5F1B nexus is a promising avenue to lower breast cancer cell metabolism and reduce cell proliferation." (PMID 37386025, 2023). "AURKA overexpression is commonly observed in many solid tumors including breast cancers, enhancing genomic instability, and is the target of several clinical trials with drugs that inhibit its activity." (PMID 37888205, 2023). "In this study, we show that AURKA promotes breast cancer-related RNA aberrant splicing in a context-dependent manner." (PMID 37415951, 2023). "In summary, we demonstrated that oncogenic AURKA promotes breast cancer-related RNA aberrant splicing in a context-dependent manner." (PMID 37415951, 2023). "The authors also reported that PHT displayed phenotypic AURKA inhibition in the breast cancer cell line MCF7, with poorly formed centrosomes and subsequent arrest in G2/M." (PMID 37174007, 2023).
breast cancer (continued). "To further investigate the implications of overexpression of Aurora A and Bcl-xL in TNBC breast cancer patients, we assessed the correlation between AURKA and BCL2L1 mRNA expression and clinical outcomes using the web-based tool KM plotter." (PMID 36077449, 2022). "FOXM1 recruits AURKA as a transcriptional factor that promotes breast cancer stem cell self-renewal and drug resistance." (PMID 35680842, 2022). "It has also been reported that alisertib, an inhibitor of AURKA, was able to treat mammary tumors when combined with PD-L1 blockade." (PMID 35311097, 2022). "Accumulating evidence indicates that AURKA is overexpressed in various cancers, including breast cancer, head and neck cancer, esophagus cancer, hematological malignancies, colorectal cancer, stomach cancer, pancreatic cancer, and ovarian and prostate cancers." (PMID 35664691, 2022). "In breast cancer, aurora kinase A (AURKA) positively regulates METTL14 protein expression by inhibiting its ubiquitylation‐mediated degradation to elevate DROSHA m6A content to improve DROSHA mRNA stability in breast cancer stem‐like cells." (PMID 34904301, 2022). "In breast cancer, excessive AURKA expression is related to drug resistance and the detrimental prognosis of patients." (PMID 35166647, 2022). "In one preclinical study, 29 breast cancer cell lines are evaluated for the sensitivity to AURKA inhibitor ENMD-2076." (PMID 33451333, 2021). "AURKA can translocate to the nucleus and enhance the phenotype of breast cancer stem cells, promoting unique oncogenic properties in malignant cells." (PMID 34675265, 2021). "It has been reported that AURKA regulates the phenotype of breast cancer tumor stem cells by modifying and stabilizing Drosha mRNA with M6A41." (PMID 34675265, 2021). "In other studies, the suppression of AURKA expression enhanced paclitaxel-induced apoptosis in numerous cancer cells including kidney and breast cancer cell lines." (PMID 32978717, 2021). "As previously reported, SHD downregulates aurora kinase A to inhibit breast cancer cell growth and ameliorate inflammatory status in breast cancer patients during the perioperative period." (PMID 34485118, 2021). "As previously reported, evidence showed that lncRNA RP11-480I12.5 promotes the progression of breast cancer cells through the miR-490-3p-AURKA-Wnt/β-catenin axis." (PMID 34702201, 2021). "Several studies have demonstrated that aberrant AURKA activity plays a key role in breast cancer progression through the development of centrosome amplification and chromosomal instability (CIN)." (PMID 33674749, 2021). "We evaluated the expression of MCM3 and AURKA by immunohistochemistry in metastatic lesions from ER+ advanced breast cancer patients treated with combined CDK4/6i and endocrine therapy (n = 86)." (PMID 33398005, 2021). "A key oncoprotein that also plays an important role in breast cancer progression is the Aurora-A serine/threonine mitotic kinase (AURKA)." (PMID 33674749, 2021). "Lapatinib also had a marked influence on reducing the AURKA expression in the breast cancer cell line compared to other drugs (p < 0.001)." (PMID 34337875, 2021). "In order to define the putative association between increased AURKA expression and shorter survival of TNBC patients, we have analyzed genome sequencing and mRNA-seq data of specimens from the TCGA and breast cancer METABRIC studies." (PMID 33674749, 2021). "Significantly, we have demonstrated the central role of AURKA in promoting drug resistance and breast cancer progression through activation of EMT reprogramming and the enrichment of highly invasive BTICs." (PMID 33674749, 2021). "High expression of both COX5A and AURKA significantly predicts poor relapse free survival (RFS) in breast cancer patients (HR = 2.400, log-rank p < 0.001)." (PMID 34593753, 2021).
breast cancer (continued). "AURKA had been well studied in many cancers, such as gastrointestinal cancer 19, colorectal cancer 20, breast cancer 21, bladder cancer 22 as well as lung cancer 23,24." (PMID 33613763, 2021). "Samples with high expression (red line) have lower percent survival and lifetime than samples with low KIF11 expression (blue line) likewise, with the overexpression of AURKA protein in breast cancer patients." (PMID 34582664, 2021). "Overexpression of AURKA has been announced in numerous cancer types, such as laryngeal, ovarian, breast cancers." (PMID 32978717, 2021). "Intriguingly, Aurora kinase A (AURKA) has been shown to limit PI3K-pathway inhibition in a breast cancer model suggesting a dependent signaling network." (PMID 34178665, 2021). "Overexpression of AURKA correlates with tumor progression and poor prognosis in various carcinomas, including pancreatic carcinoma and breast carcinoma." (PMID 35059393, 2021). "On the contrary, siRNA-mediated down-regulation of AURKA in triple-negative T47D breast carcinoma cells, which physiologically express high levels of AURKA, show a partial increase in mitochondrial mass compared with control cells." (PMID 33820826, 2021). "In Curtis Breast Statistics’ dataset, AURKA was overexpressed compared to normal samples in all breast cancer types." (PMID 33245732, 2020). "Our transcriptomic results show down-regulation of AURKA when treated with flavopiridol and dinaciclib, further suggesting the efficacy and ability of these drugs to minimize off-target effects in breast cancer." (PMID 32412527, 2020). "For instance, AURKA contributes to higher tumor grades in estrogen receptor-positive primary breast cancers." (PMID 33050100, 2020). "Our study provides the insights into the altered cell cycle signaling pathway and predicts NEK2 and AURKA kinases to be activated in breast cancer, colon cancer, LUAD, ovarian cancer, and UCEC." (PMID 32033228, 2020). "Autophagy has been shown to stimulate apoptosis-induced drug resistance in breast cancer treatment through aurora kinase A (AURKA) inhibition 79, confirming its role in tumorigenesis." (PMID 32226547, 2020). "With a combined integrative and bioinformatics approach, we identified the dysregulation in the cell cycle pathway and predicted the activation of NEK2 and AURKA across breast cancer, colon cancer, LUAD, ovarian cancer, and UCEC." (PMID 32033228, 2020). "We also found protective associations between higher GReX of AURKA (20q13.2), PIK3CA (3q26.32), and SERPINB5 (18q21.33) and lower risk of breast cancer mortality." (PMID 32079541, 2020). "Mutations in AURKA and PIK3CA have previously been shown to be significantly associated with breast cancer survival rates." (PMID 32079541, 2020). "Silence of AURKA inhibits tumor growth by inducing apoptosis and G2/M cell cycle arrest in human osteosarcoma and breast cancer." (PMID 31488217, 2019). "Unsurprisingly, higher gene expression levels of the proliferation gene AURKA indicate poorer survival in breast cancer (log rank p = 1.1e-16, n = 4,161)." (PMID 31217513, 2019). "The AURKA inhibitor alisertib synergized with tamoxifen in preclinical studies and showed activity in patients with hormone receptor-positive (HR +) breast cancer." (PMID 31254157, 2019). "In mice, the over-expression of AURKA suffices to induce the appearance of mammary tumours similar to human breast cancers." (PMID 30070631, 2018). "In endocrine-resistant, ER+ breast cancer models, alisertib, a selective inhibitor of AURKA, was found to reverse stemness reprogramming and thereby restore the CD44−/CD24+ phenotype, ERα expression, and sensitivity to endocrine therapy." (PMID 29289986, 2018). "It was shown that the Aurora kinase A inhibitor Alisertib induces cell cycle G2/M arrest and apoptosis via Akt/mTOR signaling pathways in human breast cancer cells." (PMID 29560108, 2018).